MCAM (melanoma cell adhesion molecule)
Diseases named in the same sentence as MCAM in open-access papers (continued):
Sharing a sentence is not in itself a finding about the gene and the disease.
cancer (continued). "Finally, normal D and cancer 3 retained common markers of CAPs, including RGS5, MCAM, and CRIP1, pathways relating to contractility and cytoskeletal rearrangements, and activity of transcription factors associated with muscle contractility, including MYOG." (PMID 40215177, 2025). "Interestingly, a recent study reported that MCAM was transcriptionally activated by SOX18, a subset of SOX17 interactome, which was indispensable in cancer metastasis." (PMID 40778650, 2025). "For example, ADT levels of EPCAM on cancer/epithelial cells (c0, c4, c8, c14 and c15), CD31 (PECAM1) and CD34 on endothelial cells (c7 and c9), CD146 (MCAM) on perivascular cells (c11), CD90 (THY1) and CD34 on CAFs (c13) and CD45 (PTPRC) on immune cells (c3, c5 and c12)." (PMID 33971952, 2021). "Surprisingly, some cells highly expressing GFP co-expressed MCAM (CD146), an endothelial marker but also a cellular surface receptor of different ligands, are actively involved in signaling in the numerous physiological and pathological processes involving metastases of different cancer types." (PMID 36233261, 2022). "Here, we investigated the potential therapeutic properties of anti-sMCAM mAb on mouse MC38 cells, and two human CRC cancer cell lines (DLD1, membrane MCAM positive, and Lovo, membrane MCAM negative)." (PMID 38137406, 2023). "On the contrary, MMP9 seemed completely nonspecific and not correlated to an increase in cancer cell aggressiveness, while other genes such as VIM, CDH5, and MCAM showed a trend toward an increased expression in the metastatic counterpart, albeit not statistically significant." (PMID 40332096, 2025).
infection (12 papers, 2016 to 2025). The state of being infected such as from the introduction of a foreign agent such as serum, vaccine, antigenic substance or organism. "Our results showed that BAE cell infection by E. ruminantium resulted in the over-expression of several ECs surface proteins, such as ICAM1, VCAM1, CSF1, ESM1 and MCAM." (PMID 34073568, 2021).
adenocarcinoma (7 papers, 2013 to 2025). A common cancer characterized by the presence of malignant glandular cells. "To investigate the relationship between MCAM expression and histological differentiation in human GC tissues, we performed immunohistochemical (IHC) staining on a series of gastric tissue samples ranging from normal gastric epithelium to poorly differentiated adenocarcinomas." (PMID 40924339, 2025).
colorectal (3 papers, 2023 to 2025). "Consequently, we selected eight statistically significant TACTs—EPCAM, KRT19, ERBB2, MKI67, MCAM, FOXA2, SNAI2, and NPTN—which we designated as colorectal TACTs (C-TACTs)." (PMID 40003943, 2025).
MCAM also shares sentences with these, for which no sentence is quoted: atherosclerosis (11 papers); endothelial dysfunction (10); lymph node metastasis (8); cutaneous melanoma (7); systemic sclerosis (7); cardiovascular disease (6); colon cancer (6); Arthritis (5); cerebral malaria (5); clear cell renal cell carcinoma (5); colitis (5); COVID-19 (5); myocardial infarction (5); nasopharyngeal carcinoma (5); pulmonary arterial hypertension (5); angiosarcoma (4); chronic renal failure (4); Crohn disease (4); diabetes (4); metastatic cancer (4); prostate adenocarcinoma (4); Stroke (4); brain tumor (3); esophageal squamous cell carcinoma (3); head and neck squamous cell carcinoma (3); inflammation (3); inflammatory bowel disease (3); intrahepatic cholangiocarcinoma (3); leiomyosarcoma (3); Lipedema (3).
A further 164 diseases each share a sentence with MCAM in 3 papers or fewer.